EGFR (epidermal growth factor receptor)
Diseases named in the same sentence as EGFR in open-access papers (continued):
Sharing a sentence is not in itself a finding about the gene and the disease.
tumor (continued). "The nanosized micelles demonstrated high internalization of the anti-EGFR antibody in the A431 tumor cells, and the use of doxorubicin with the antibody produced extensive cytotoxicity in an in vitro analysis in EGFR-overexpressing cell lines." (PMID 33291312, 2020). "The secreted HB-EGF binds to EGFR, leading to invadopodia formation in tumour cells in a hypoxic environment." (PMID 32386517, 2020). "On the other hand, even in AXL-low-expressing EGFR-mutated NSCLC, a small population of tumor cells persist to osimertinib and develop acquired resistant tumors." (PMID 32929081, 2020). "To determine if the observed increase in EGFR level was driven by tumor plasma cells and related to tumor progression, we set up a coculture experimental system mimicking interactions between endothelial and plasma cells during tumor growth." (PMID 31936715, 2020). "ABT-414 and ABBV-322 resulted in significant tumor growth inhibition in MM models with high EGFR and mAb806 epitope expressions." (PMID 33023139, 2020). "Erlotinib 100 mg/d was comparable to gefitinib 250 mg/d in terms of disease control, tumor response, PFS, OS, and toxicity, supporting the use of 100 mg/d erlotinib in patients with EGFR-mutated, advanced NSCLC." (PMID 33244458, 2020). "Within the tumor microenvironment, recruited TAMs produce EGF to which tumor cells respond through the epidermal growth factor receptor (EGFR) present on their cell surface, enhancing cell invasion and migration." (PMID 32867288, 2020). "It is well established that activation of EGFR signaling plays critical roles in promoting multiple tumor cell proliferation, migration, therapeutic resistance and cancer stem cell self-renewal maintenance." (PMID 33643898, 2020). "Currently, tumor genotyping is critical as personalized treatment for EGFR, ALK, ROS1, BRAF in the first-line setting." (PMID 32525942, 2020). "DCN can also exert tumor-suppressive functions via affecting multiple other signaling pathways, including EGFR, IGFR1, AKT, and cMYC." (PMID 32553107, 2020). "IHC staining of the tumor xenografts showed the heavy staining of phospho-EGFR (pEGFR) and EGFR in untreated H1975 tumor xenografts, whereas weak staining of pEGFR and EGFR was detected in HGK-treated tumor." (PMID 32093124, 2020). "NPs modified with cetuximab (an antibody used to target EGFR) were internalized via EGFR-mediated endocytosis and exhibited large tumor-homing potential because of the combination regimen." (PMID 32977707, 2020). "The association rates (i.e., kon) between cetuximab and its target EGFR in both tumor compartments were estimated to be close and were therefore considered as a shared parameter in the two tumor compartments." (PMID 33028895, 2020). "We suggest that treatment with DTIP should start immediately after diagnosis (before extensive tumor development) and should be administered in conjunction with EGFR inhibitors." (PMID 32647187, 2020). "Compared to ERhi cases, ERlo cases were associated with larger tumour, higher grade, more necrosis, more sTIL, higher pN stage, high KI67, HER2, EGFR and CK5/6 positivity but PR and AR negativity (p ≤ 0.039)." (PMID 32713939, 2020). "For example, EGFR in-frame mutations can constitutively activate the receptor, making anti-EGFR antibodies ineffective for tumor suppression." (PMID 32722184, 2020). "Numerous studies were aimed at selecting inhibitors, including aptamers, for EGFR because it is a relevant feature in primary GBM (it is overexpressed in 60% of tumors) and its mutation correlates with poor prognosis and tumor aggressiveness." (PMID 32764266, 2020). "By observing the effects of HGF, c‐MET amplification, and EGFR‐T790M tumor on PD‐L1 expression and immune escape ability before and after EGFR‐TKIS drug resistance, the regulation mechanism of PD‐L1 in different drug‐resistant subtypes was discussed." (PMID 32875727, 2020).
tumor (continued). "The reduced efficacy of the EGFR inhibitor (cetuximab) is due to the adverse effect of the over methylation of the MSI-H tumor on the EGFR inhibitor, resulting in the low expression of the EGFR ligand." (PMID 31956294, 2020). "Among EGFR‐wt patients, a better ECOG PS (<2) and low tumor differentiation grade was independently associated with a better OS (26.6 months vs 15.4 months; P = .001 and 23.3 vs 14.9 months, P = .042, respectively)." (PMID 32043750, 2020). "We found that persistent high expression of SIAH in residual tumors reflects activation of the “tumor-driving” K-RAS/SIAH/EGFR pathway that fuels tumor growth and metastatic spread of disseminated and residual chemo-resistant tumor clones remaining after NACT." (PMID 32846967, 2020). "We investigated Rab8 and Rabin8 function using the C. elegans tumor model to understand the role of vesicle trafficking during multivulva development induced by EGFR T790M-L858R." (PMID 33092268, 2020). "NB-PS conjugates 7D12-PS and 7D12-9G8-PS targeting EGFR showed significant tumor localization in vivo, which was higher for 7D12-9G8-PS." (PMID 32089747, 2020). "The high expression of EGFR has been reported to be related to advanced tumor stages, resistance to therapies, poor prognosis, and increased metastasis." (PMID 33273921, 2020). "The PDX-1 tumor growth rate was significantly lowered by KYA1797K treatment (p < 0.01), and the reduction in β-catenin, pan-RAS, and EGFR expression levels in tumor tissues was confirmed." (PMID 32457491, 2020). "We therefore strongly recommend a ‘liquid re-profiling’ when more than 10 distinct tumor masses are displayed at the CT scan before starting a first-line treatment containing an anti-EGFR antibody." (PMID 33383664, 2020). "Other investigators used NGS to analyze 54 genes and copy number variants in three genes (EGFR, ERBB2 and MET) on ctDNA of patients with various tumor types." (PMID 32010431, 2020). "The concordance with tumor tissue biopsy for clinically relevant alterations in EGFR is comparable with that of the approved liquid Cobas EGFR test." (PMID 32596507, 2020). "Nevertheless, we obtained similar results when the analysis was limited to patients in whom the tumor PD-L1 status was evaluated in tumor tissue specimens obtained before the initiation of EGFR-TKI treatment." (PMID 33255696, 2020). "A relevant aspect of the cutaneous alterations provoked by EGFR inhibitors is the chance that they can require an interruption in anti-tumor treatment; however, there is a complete accord that suspension of anti-EGFR treatment-based therapy should be avoided." (PMID 33375183, 2020). "The ratio of CD8 tumor infiltration lymphocytes was significantly lower in EGFR‐mutant than in wild‐type patients (P = 0.026)." (PMID 32500560, 2020). "Only in four of the 11 discordant FISH-detected EGFR amplified cases were different tumor blocks used by FISH and FM." (PMID 32118206, 2020). "In MOC2-huEGFR tumors, combining radiation and cetuximab induced tumor growth delay that required NK cells, EGFR expression, and FcγR on host immune cells." (PMID 33281820, 2020). "EGFR can be directly targeted by miR-34a through upregulation due to the tumor suppressive abilities of miR-34a." (PMID 32316322, 2020). "Alterations of EGFR expression or of the ErbB signaling pathway are involved in tumor growth, angiogenesis, invasion, metastasis, and apoptosis inhibition." (PMID 33050158, 2020). "These specificity tuned PINs containing high PS payloads demonstrated up to 100-fold cancer cell binding specificities and efficient photodynamic destruction in tumor cells and nodules over-expressing cell surface EGFR." (PMID 32726945, 2020).
tumor (continued). "Despite the impressive anti-tumor activity of osimertinib in epidermal growth factor receptor (EGFR) T790M-positive non-small cell lung cancer (NSCLC) patients, 30–40% of patients still show limited response." (PMID 32067121, 2020). "It has been shown that the MMP7, LAMC2, and EGFR expressions were correlated with tumor aggressiveness, advanced T grade, and tumor stage in GC tumors." (PMID 32467737, 2020). "Biological responses to EGFR signaling are pleiotropic and can result in tumor-promoting processes, including enhanced cell motility." (PMID 33204681, 2020). "Our previous report demonstrated the multivulva (Muv) phenotype, a tumor model in C. elegans (jgIs25 strain) by engineering LET-23/EGFR with a TKI-resistant human EGFR T790-L858 mutant." (PMID 33092268, 2020). "With SEQ, 275 FFPE tumor samples received at MODL were screened for sequence variations in EGFR TKD (exons 18, 19, 20, and 21)." (PMID 32962681, 2020). "Our work provides new insights into how tumour heterogeneous promotes drug resistance in acquired EGFR‐TKI resistance." (PMID 31894895, 2020). "EGFR was expressed membranous in 94% of the tumor tissue and showed overexpression compared to normal mucosa in 46% of the cases." (PMID 33202816, 2020). "Another study found that ultrasound-guided PAI and anti-epidermal growth factor (EGFR) antibody conjugated to gold nanorods can effectively detect EGF-expressing primary tumour and regional lymph node metastases." (PMID 32872399, 2020). "In both cell lines, the inhibition of the EGFR pathway was also compensated by over-expression of EGF by tumor cells only for the triple combination." (PMID 31938054, 2020). "Unregulated activity of the EGFR mediates proliferation, invasion, migration, and angiogenesis, which promote the progression of tumor cells." (PMID 33126605, 2020). "Both c-Src and EGFR have been found co-overexpressed in several types of tumor, including glioblastomas and carcinomas of the colon, breast, and lung." (PMID 32517369, 2020). "This hypothesis is supported by the observation that the development of resistance to EGFR inhibition is associated with downregulation of mismatch and homologous recombination repair proteins resulting in error-prone DNA repair and increased tumor variagenic ability." (PMID 32379280, 2020). "Tumor proliferation increases and resistance to cetuximab, a widely used EGFR inhibitor in clinical practice, is established." (PMID 32799866, 2020). "According to the CRC Subtyping Consortium, consensus molecular subtype 2 (CMS2) is predominantly distributed in left-sided tumours and shows activated EGFR-dependent signalling defined by the over-expression of EGFR." (PMID 33188279, 2020). "Hyperprogression occurred more often in case of MDM2/4 or EGFR amplification or <1% PD-L1 positive tumor cells." (PMID 32110946, 2020). "EGFR inhibitors (EGFRi) can decrease the radioresistance of tumor cells, and EGFR-mutant cell lines show higher radiosensitivity than wild-type cells." (PMID 33299643, 2020). "It has been reported that EGFR-TKI treatment can select CEA-positive clones from a CEA-negative primary tumor, resulting in tumor progression." (PMID 32034239, 2020). "It has been reported that coactivation of EGF and EGFR drives tumor metastasis via PI3K/AKT-dependent pathways." (PMID 32045997, 2020). "This chimera was shown to induce apoptosis effectively both in vitro and in vivo, and inhibit tumor growth and angiogenesis in the C4-2 PCa xenograft model by an EGFR-HIF1α-VEGF-dependent mechanism." (PMID 33287240, 2020). "Depatuxizumab mafodotin is an anti-EGFR ADC targeting a tumor-selective cryptic epitope on the CR1 domain of EGFR." (PMID 32111076, 2020). "Further, acquisition of stemness phenotype after the emergence of EGFR-TKI resistance enhanced tumor metastasis in lung cancer." (PMID 32820157, 2020). "Acinar, though, accreting with other components more frequently exhibited EGFR wild-typed in tumor parenchyma." (PMID 32093629, 2020).
tumor (continued). "Intravital microscopy imaging was performed to determine potential differences in the distribution between the two EGFR-targeted NB-PS in tumor and in normal tissue immediately surrounding the tumor." (PMID 32089747, 2020). "Crosstalk between the tumor ECM and growth factor receptors (like EGFR) has been further shown to play an important functional role in mediating tumor progression and metastasis." (PMID 32719793, 2020). "In all cell lines, increased expression of EGFR (IHC) was shown in tumor cells co-cultured with CAFs compared to spheroids composed solely of tumor cells." (PMID 33353547, 2020). "A single patient harbored an EGFR amplification in 5% of tumor cell nuclei, and this was considered non-amplified both by FISH and by dPCR." (PMID 32303258, 2020). "CS nanocapsules carrying EGFR and galectin-1 siRNA significantly increased survival in tumor-bearing mice and decreased gene expression in tumor tissue." (PMID 32849207, 2020). "Activation of EGFR pathway was shown to promote tumor cell growth, invasion and angiogenesis, prevent apoptosis, and induce chemoresistance and radioresistance." (PMID 33008416, 2020). "We found that the GEM is a local drug delivery (LDD) device capable of delivering gemcitabine to tumors and inhibiting tumor cell growth, angiogenesis, and metastasis by suppressing EGFR signaling pathways." (PMID 32111094, 2020). "Taken together, our results reveal increased cell proliferation and elevated expression of EGFR in HNSCC tumor spheroids in the presence of CAFs." (PMID 33353547, 2020). "The observed 24 h residual accumulation of the untargeted agent in the EGFR(-) tumor line is a stark indicator of this challenge, suggesting that even at this long time period, non-specific retention can be a dominant source of agent uptake in some tumors." (PMID 33042280, 2020). "Nevertheless, although diabetes has been shown to be associated with more rapid progression of GBM and higher patient mortality, the connection with the levels of FPR1 and EGFR in tumor remains to be established in the clinic samples." (PMID 32038501, 2020). "It has been shown that the EGFR up regulation and ErbB4 down regulation were significantly correlated with tumor aggressiveness, advance grade, and poor overall survival in a sub population of BCa patients." (PMID 32795296, 2020). "Among these DEGs, EGFR was selected for further investigation because it plays important roles in the regulation of several pathways related to tumour growth and metastasis." (PMID 32210368, 2020). "EGFR was responsible for the tumor invasiveness, which is an interesting finding that EGFR mutations were associated with lower SUVmax." (PMID 32742498, 2020). "Hippo pathway components were enriched among the orthologs cooperating with EGFR to drive tumor formation." (PMID 32737065, 2020). "HBEGF serves as a crucial component of EGFR, mediating tumor cell proliferation and bringing about cetuximab resistance." (PMID 33193693, 2020). "Angiogenesis and activation of the epidermal growth factor (EGFR) pathway play an essential role in tumor proliferation and metastasis." (PMID 32337094, 2020). "The epidermal growth factor receptor (EGFR) induces tumor angiogenesis by the activation of the autocrine VEGF/VEGFR-2 pathway in endothelial cells." (PMID 32204455, 2020). "Altogether, these results indicate that the GEM suppressed the EGFR signaling pathway and arrested the cell cycle to inhibit tumor growth." (PMID 32111094, 2020). "This review will help us better understand the latest battles between EGFR monoclonal antibodies and resistant tumor cells, and the future directions to develop anti-tumor EGFR monoclonal antibodies with durable effects." (PMID 32793499, 2020). "We performed a prospective screening of genetic alterations in tumour tissue of patients with EGFR-ALK-ROS1 wild-type advanced NSCLC." (PMID 32376889, 2020).
tumor (continued). "ALIX downregulation promotes tumor survival through enhancement of EGFR activation, and through PD-L1 membrane accumulation, leading to immunosuppression." (PMID 32923684, 2020). "In EGFR WT A549 and L858R/T790M mutant H1975 xenograft tumors, gefitinib had no visible effect on tumor growth, whereas deguelin markedly reduced tumor size at the treatment endpoint." (PMID 32081857, 2020). "Both the EGFR signaling pathway and survivin are involved in cancer cell proliferation, tumor vascularization, and metastasis." (PMID 33287240, 2020). "Members of the epidermal growth factor receptor family (EGFR-ErbB4) have been involved in the development of human neoplasia." (PMID 32423101, 2020). "Exosomes released by EGFR-bearing tumor cells are taken up by neighboring endothelial cells and can accelerate the growth of the tumor cell." (PMID 32859053, 2020). "More importantly, these genes function like classical tumor suppressors as, when downregulated in the background of overexpressed Yki or EGFR, we observed neoplastic growth." (PMID 32737120, 2020). "Sixty-one of the patients (38 sensitive and 23 resistant to EGFR blockade) were included in the study, as they met the inclusion criteria and quality of tumor DNA was good." (PMID 32796636, 2020). "The EGFR detection rate was 53 and 83% among samples with a tumour content ratio < 10% and ≥ 10%, respectively." (PMID 32028905, 2020). "In the context of nanobodies, a BiTE targeting the EGFR and Vγ9Vδ2 TCR stimulated T-cell mediated cytotoxicity against EGFR+ tumor cells in vivo." (PMID 32793488, 2020). "Interaction proteomics is required to analyse potential interaction partners and reveal the degradation mechanism of EGFR in tumour cells upon DPBA binding." (PMID 33033232, 2020). "According to recent studies, the oncogenic events in cancer cells (such as the expression of mutant K-ras, EGFR) lead to the increased TF levels and activity, which thereby promoting tumor aggressiveness, angiogenesis, and hypercoagulability." (PMID 33243184, 2020). "miR-21 have shown upregulation in NSCLC, demonstrating how EGFR can function as a regulator for potential tumor progressive non-coding RNAs." (PMID 32316322, 2020). "Most sections stained intensely for αvβ6 and epidermal growth factor receptor (EGFR) on tumor cells." (PMID 32516897, 2020). "Expression of mutant EGFR was sufficient to induce PD-L1 expression in bronchial epithelial cells, while EGFR targeting reduced PD-L1 expression in EGFR-mutant tumor cells." (PMID 32992658, 2020). "Our tumor model experiments also point out that inhibiting EGFR–ERK function and abrogating ILF3/SGOC activity in tumors are effective for metabolism-targeted therapies." (PMID 31772275, 2020). "Conditioned medium from high EGFR-expressing tumor cells treated with NB-PDT led to the maturation of human dendritic cells, as indicated by the upregulation of CD86 and MHC II on their cell surface, and the increased release of IL-12p40 and IL-1β." (PMID 32326519, 2020). "Tumor invasion, angiogenesis, cellular proliferation, and apoptosis is controlled by epidermal growth factor receptor (EGFR)/ErbB1 in NSCLC." (PMID 32752229, 2020). "To explore the anti-tumor activity of deguelin in vivo, we performed mice xenograft models using WT EGFR and mutant EGFR expressing NSCLC cells, including A549, HCC827, H3255, and H1975 cells." (PMID 32081857, 2020). "Blocking EGFR or MET alone for tumor suppression can lead to cell survival by activating other alternative pathways." (PMID 32070026, 2020). "Expression of AXL in the cell cytoplasm of pre-EGFR-TKI-treated tumor samples was evaluated using immunohistochemistry (IHC) staining and scored as very high (3+), high (2+), low (1+), and no expression of AXL." (PMID 32929081, 2020).